LIG4 (DNA ligase 4)
Diseases named in the same sentence as LIG4 in open-access papers (continued):
Sharing a sentence is not in itself a finding about the gene and the disease.
microcephaly (21 papers, 2012 to 2025). A congenital or acquired developmental disorder in which the circumference of the head is smaller than normal for the person's age and sex. "In a LIG4 (Lig4Y288C) mouse model analyzed for its susceptibility to IR, microcephaly was proposed to occur due to apoptosis resulting from persisting DSBs in the intermediate zone arising from the transit of damaged cells coming from the VZ and SVZ." (PMID 37881689, 2023). "In contrast, DNA Ligase 4 (LIG4) deficiency results in a variable phenotypic spectrum of growth failure, microcephaly, developmental delay, and a tendency to develop bone marrow failure, myelodysplasia, and/or malignancies." (PMID 34716846, 2022). "Extreme growth failure and microcephaly is a common and early presentation of LIG4 deficiency patients." (PMID 34630384, 2021). "The phenotypic features are similar to those of patients with NBS and LIG4 deficiency, namely profound microcephaly with variable degrees of learning difficulty, growth failure, SCID or CID." (PMID 32648006, 2020). "This work extends the phenotypic spectrum associated with LIG4 mutations, establishing that extreme growth retardation with microcephaly is a common presentation of bilallelic truncating mutations." (PMID 24123394, 2014). "In the nervous system mutation or deletion of the NHEJ core components Lig4 or XRCC4 causes microcephaly, neuronal death during development, and promotes medulloblastomas with recurrent chromosome alterations." (PMID 23861962, 2013). "Individuals with mutations in LIG4 exhibit immunodeficiency, developmental delay, growth retardation, and microcephaly, a disease that has been termed LIG4 syndrome." (PMID 22737170, 2012). "Thus, significant microcephaly and growth restriction are regarded as the most prominent features of LIG4 deficiency patients." (PMID 34630384, 2021). "LIG4 deficiency may lead to impaired prenatal differentiation of neuronal cell and result in microcephaly and developmental delay." (PMID 34630384, 2021). "Three patients with T-B-NK + phenotype with microcephaly were diagnosed by NGS: NHEJ1 variant was detected in 2 siblings from the same family and LIG4 in another patient." (PMID 35482138, 2022). "In humans, hypomorphic mutations in DNA ligase IV confer LIG4 syndrome, which is characterised by immunodeficiency, microcephaly and developmental delay." (PMID 26303202, 2015). "However, considering the high level of apoptosis detected in Lig4-deficient mice, it is possible that LIG4 syndrome patients also experience elevated neuronal apoptosis during development, this possibly underlying the reported microcephaly and developmental delay." (PMID 22737170, 2012). "Similarly, microcephaly also results from mutation in genes associated with S phase progression (ATR, ATRIP, CtIP—Seckel syndrome; DNA ligase IV—lig4 syndrome; XRCC4—microcephalic primordial dwarfism)." (PMID 34035299, 2021). "LIG4 mutations should also be considered in the differential diagnosis of Fanconi anemia syndrome, especially in patients with microcephaly and growth failure but without limb reduction defects." (PMID 24123394, 2014). "In accordance, a recent study of a knock in Xrcc4M61R mouse model avoiding Lig4 disruption showed rescued embryonic lethality and only a modest increase in apoptotic cells in the intermediate zone, indicating that microcephaly in XRCC4 syndrome may arise due to LIG4 destabilization." (PMID 37881689, 2023). "Most patients with LIG4 mutations had dysmorphic features (“Seckel-like” facies, epicanthal folds, up- or down-slanted palpebral fissures), IUGR, microcephaly, short stature and developmental delay, although not all." (PMID 24892279, 2014).
LIG4 syndrome (20 papers, 2007 to 2025). "LIG4 syndrome is caused by homozygous or, more often, compound heterozygous hypomorphic mutations in the LIG4 gene." (PMID 38933494, 2024). "LIG4 syndrome is caused by homozygous or compound heterozygous mutations in the LIG4 gene, and the most common genotype is p.R814X/p.K424Rfs*20." (PMID 32471509, 2020). "Renal imaging would be appropriate in all individuals with LIG4 syndrome to establish the relationships between LIG4 variants and renal tract disease." (PMID 32534991, 2020). "DNA ligase IV deficiency is a rare primary immunodeficiency, LIG4 syndrome, often associated with other systemic features." (PMID 27717373, 2016). "Considering that the mutations of all the other DSB repair proteins upstream LIG4 are lethal, the LIG4 syndrome might be the only viable radiosensitive human syndrome directly caused by the loss of the function of its associated protein." (PMID 34281212, 2021). "Hypomorphic mutations of LIG4 cause a rare disease known as LIG4 syndrome." (PMID 23523427, 2013). "DNA Ligase IV (LIG4) syndrome, also known as DNA Ligase IV deficiency or Ligase 4 syndrome, is a very rare autosomal recessive disorder that also belongs to the group of hereditary diseases associated with defects in cellular responses to DNA damage." (PMID 38933494, 2024). "DNA ligase IV (LIG4) syndrome is an exceptionally rare autosomal recessive disorder that belongs to the group of hereditary diseases associated with impaired DNA damage-response mechanisms." (PMID 32471509, 2020). "In previously reported cases, only one patient with LIG4 syndrome was documented to present a phenotype that mimicked Bechet’s disease (BD), and one female patient who was diagnosed with IBD harbored a heterozygous stop-gain (p.R814X) variant in the LIG4 gene." (PMID 32471509, 2020). "LIG4 catalyzes double-strand break repair by joining non-homologous ends, and mutation in LIG4 causes LIG4 syndrome." (PMID 24969172, 2014). "Indeed, mutation of the genes encoding DNA ligase IV (LIG4), Nibrin (NBS1) or Aprataxin (APTX) results in DDR disorders, specifically LIG4 syndrome, Nijmegen breakage syndrome (NBS) and Ataxia oculomotor apraxia-1, in association with increased radiosensitivity." (PMID 26208712, 2015). "The fact that knockout mice lacking functional Lig4 are not viable indicates that the mutations in the LIG4 syndrome patients might be hypomorphic alleles." (PMID 22737170, 2012). "Interestingly, impairment of DNA ligase IV (LIG4), nibrin (NBS1), or aprataxin (APTX) activity as a result of genes’ deleterious mutation leads to severe disorders in DNA damage response known as LIG4 syndrome, Nijmegen breakage syndrome (NBS), and Ataxia oculomotor apraxia-1." (PMID 36340042, 2022). "It should be pointed out, however, that HSCT in our LIG4-patient was prompted by bone marrow hypo-and dysplasia rather than by a SCID phenotype as in other patients with LIG4 syndrome." (PMID 17224058, 2007).
breast carcinoma (19 papers, 2007 to 2024). "The predicted direction of association with contralateral breast cancer risk was uniformly increased for the LIG4, NHEJ1, and XRCC5 genes while uniformly decreased for the XRCC4 and XRCC6 genes." (PMID 31560388, 2019). "Downregulated LIG4 and/or Artemis were detected before in cell lines established from high-risk neuroblastomas and therapy-resistant breast carcinomas." (PMID 27705909, 2016). "Lig4 is frequently amplified, resulting in elevated mRNA expression in patients with basal breast cancer." (PMID 30838131, 2019). "We anticipate Lig4 depletion will enhance the efficaciousness of ionizing radiation in breast cancer treatment." (PMID 30838131, 2019). "Amplifications in LIG4 are observed in 1.8% of all breast cancers represented in the 2509 samples in the METABRIC dataset (accessed in August 2018)." (PMID 30838131, 2019). "Our investigations focused on triple negative breast cancer cells, as, compared to nonbasal breast cancer, LIG4 is frequently amplified, and an increased gene dose is associated with higher Lig4 expression." (PMID 30838131, 2019). "When XRCC4 or LIG4 were depleted in the EEPD1/RAD52 co-depleted BRCA1-deficient breast cancer cells, no significant reduction in cell survival was observed." (PMID 29145865, 2017). "However, the expression of these up-regulated ones were decreased once pyrvinium pamoate was added, among which several (breast cancer susceptibility gene (BRCA2), DNA ligase IV (LIG4) as well as recombinase RAD51) exhibited significantly decreased P-values as compared with doxorubicin alone group." (PMID 27303922, 2016). "Subsequently, it was discovered that the overexpression of RUVBL1/DTL greatly increased the expression of NHEJ repair pathway molecules, namely K70, K80, DNA-PKcs, 53BP1, LIG4, and XRCC4, within breast cancer cells." (PMID 38609375, 2024). "To investigate the role of Lig4 in breast cancer, especially TNBC, we depleted Lig4 in basal breast cell lines and confirmed the knockdown using qPCR and western blot." (PMID 30838131, 2019). "As such, inhibition of Lig4 may prove beneficial in combination with therapeutic application of the FDA-approved breast-specific stereotactic body radiotherapy device GammaPod, which delivers a high (8 Gy), but localized dose of radiation for breast cancer treatment." (PMID 30838131, 2019). "To assess the prevalence of LIG4 genetic alterations in basal versus non-basal breast cancer, we interrogated METABRIC cohort of breast cancer patients characterized in the Cancer Genome Atlas (TCGA) using cBioPortal." (PMID 30838131, 2019).
glioma (17 papers, 2011 to 2026). A benign or malignant brain and spinal cord tumor that arises from glial cells (astrocytes, oligodendrocytes, ependymal cells). "VPA, in combination with BMN-673 or TMZ, had an influence on clonogenic efficacy, while the triple combination of VPA + BMN673 + TMZ was able to almost completely abolish the clonogenic growth of LIG4-deficient glioma cells." (PMID 37763083, 2023). "LIG4 rs1805388 were associated with an increased risk of gliomas among smokers under a dominant model." (PMID 23663450, 2013). "In the single-locus analysis there was a significant association between gliomas and the LIG4 rs1805388 (Ex2 +54C>T, Thr9Ile) TT genotype (adjusted OR, 3.27; 95% CI, 1.87-5.71), as well as the TC genotype (adjusted OR, 1.62; 95% CI, 1.20-2.18)." (PMID 23663450, 2013). "Compared with never-smokers carrying the wild-type genotype of LIG4 rs1805388, those ever-smokers with variant-containing genotype of LIG4 rs1805388 polymorphism had a significantly increased risk to develop gliomas (adjusted OR, 1.67; 95% CI, 1.11-2.50)." (PMID 23663450, 2013). "Previous researches on the function of the XRCC4 rs1805377 and LIG4 rs1805388 polymorphisms have been informative in understanding the potential roles of these two polymorphisms in the development of gliomas." (PMID 23663450, 2013). "First, we were not able to explore the exact biological mechanism of how XRCC4 rs1805377 and LIG4 rs1805388 polymorphisms affect the development of gliomas." (PMID 23663450, 2013). "When we stratified our analysis by smoking status, LIG4 rs1805388 was associated with an increased glioma risk among smokers." (PMID 23663450, 2013). "XRCC4 rs1805377 and LIG4 rs1805388 polymorphisms may be useful susceptibility biomarkers for gliomas and aid in the development of diagnostic strategy to reduce the burden of gliomas." (PMID 23663450, 2013). "In comparison with the reference combination of LIG4 rs1805388 CC and XRCC4 rs1805377 AA, the combination of the LIG4 rs1805388 CT+TT genotype together with XRCC4 rs1805377 AG+GG genotype was found to be significantly associated with glioma (adjusted OR, 2.22; 95% CI, 1.49-3.30)." (PMID 23663450, 2013). "In conclusion, of the 10 potential functional polymorphisms investigated here, we provide the first evidence that the XRCC4 rs1805377 (IVS7-1A>G, splice-site) and LIG4 rs1805388 (Ex2 +54C>T, Thr9Ile) polymorphisms contribute to the risk of developing gliomas, alone or in combination." (PMID 23663450, 2013). "We further evaluated the interaction between the LIG4 rs1805388 and XRCC4 rs1805377 polymorphisms and tobacco smoking with respect to the risk of gliomas." (PMID 23663450, 2013). "We detected a significant additive (Pinteraction = 0.013) and multiplicative interaction (Pinteraction = 0.046) effect between LIG4 rs1805388 and tobacco smoking for the development of gliomas." (PMID 23663450, 2013). "Treatment with TSA that inhibits multiple HDACs causes efficient, reversible chromatin hyperacetylation in Lig4-/- MEFs, as well as in human HCT116 Lig4-/- cells and the human glioma cell line M059K." (PMID 22908892, 2012). "Two recent genome-wide association studies (GWAS) of risk of glioma in European populations did not identify an association between the XRCC4 rs1805377 and LIG4 rs1805388 polymorphisms and glioma risk." (PMID 23663450, 2013). "Interestingly, we detected a significant additive and multiplicative interaction effect between the LIG4 rs1805388 and XRCC4 rs1805377 polymorphisms with an increasing risk of gliomas." (PMID 23663450, 2013).
glioma (continued). "Furthermore, significant more-than-multiplicative (0.005) and more-than additive (0.009) gene-gene interactions of these two loci (LIG4 rs1805388 CT+TT and XRCC4 rs1805377 AG+GG) were found in relation to the risk of gliomas." (PMID 23663450, 2013). "Thus, we estimated the combined effect of LIG4 and XRCC4 genes on glioma risk." (PMID 23663450, 2013). "Here we investigate the role of 10 potential SNPs in XRCC3, BRCA2, RAG1, XRCC5, LIG4, XRCC4 and ATM in the development of gliomas, and further evaluate their gene-gene and gene-environment interactions in the development of glioma." (PMID 23663450, 2013). "We genotyped 10 potentially functional single nucleotide polymorphisms (SNPs) in 7 DNA double-strand break repair pathway genes (XRCC3, BRCA2, RAG1, XRCC5, LIG4, XRCC4 and ATM) in a case–control study including 384 glioma patients and 384 cancer-free controls in a Chinese Han population." (PMID 23663450, 2013).
severe combined immunodeficiency (14 papers, 2007 to 2026). Severe combined immunodeficiency (SCID) comprises a group of rare monogenic primary immunodeficiency disorders characterized by a lack of functional peripheral T lymphocytes resulting in early-onset severe respiratory infections and failure to thrive. "Abnormal LIG4 expression has been detected in prostate or colorectal cancer, and LIG4 mutations have also been found in Omenn syndrome, which is a form of severe combined immunodeficiency." (PMID 37233261, 2023). "DNA ligase IV deficiency is a rare form of autosomal recessive, radiosensitive severe combined immunodeficiency (SCID), which is caused by hypomorphic mutations of the DNA ligase IV (LIG4) gene." (PMID 31604460, 2019). "Among the 52 patients, 3 (5.8%) were diagnosed with severe combined immunodeficiency (SCID): 1 patient had ADA deficiency, and two patients had DNA ligase IV deficiency (LIG4)." (PMID 41705238, 2026). "Rare mutations in LIG4 (encoding DNA ligase IV), XLF, DCLRE1C (encoding Artemis) or PRKDC (encoding DNA-PKcs) have been identified in a radiosensitive sub-class of patients with severe combined immunodeficiency (SCID) and can predispose to cancer." (PMID 31921645, 2019). "Consequently, disruption of NHEJ proteins (Ku, DNA-PKcs, XLF, LIG4, and Artemis) often results in defects in DSB repair, radiation sensitivity, and severe combined immunodeficiency (SCID)." (PMID 25872942, 2015). "Mutations in genes that affect the development or function of T and B cells [DCLRE1C(ARTEMIS), ZAP70, RAG1/2, IL2RG, ILRA7, LIG4, JAK3, ADA] can result in intestinal inflammation along with recurrent infections from severe combined immunodeficiency (SCID)." (PMID 34122435, 2021). "Therefore, defects in NHEJ factors critical for V(D)J recombination, such as Artemis, DNA-PKcs or LIG4, might lead to partial or complete absence of specific immune cells, resulting in a broad spectrum of immunodeficiencies, including severe combined immunodeficiency (SCID)." (PMID 32664329, 2020).
Nijmegen breakage syndrome (13 papers, 2007 to 2024). Nijmegen breakage syndrome is a rare genetic disease presenting at birth with microcephaly, dysmorphic facial features, becoming more noticeable with age, growth delay, and later-onset complications such as malignancies and infections. "The same issues regarding sensitivity to radiation and alkylating agents applies to these patients as to those with DNA ligase 4 deficiency, Cernunnos-XLF deficiency and Nijmegen breakage syndrome." (PMID 34226669, 2021). "One large multicenter study looked at outcomes of transplant for patients with DNA ligase 4 deficiency (36 patients), Cernunnos-XLF deficiency (17 patients) and Nijmegen breakage syndrome (26 patients)." (PMID 34226669, 2021). "The deletion of KPNA2 and its association with NBN links Patient 3 to Patients 1 and 2 and the well-established phenotypic overlap of LIG4 and Nijmegen breakage syndrome." (PMID 24892279, 2014). "Like in Fanconi anemia and a single previously reported patient with the Nijmegen breakage syndrome, our patient illustrates that HSCT can be an effective treatment of LIG4-deficiency." (PMID 17224058, 2007). "After exclusion of the Nijmegen breakage syndrome by mutation analysis and exclusion of AT on clinical grounds (supported by normal AFP levels), sequencing of the LIG4 gene established the diagnosis of DNA ligase IV deficiency syndrome." (PMID 17224058, 2007). "Microcephaly with bird-like facial dysmorphia may be observed at birth in cases of DNA Ligase IV deficiency (LIG4), Nijmegen breakage syndrome (NBS1), and Cernunnos-NHEJ1 deficiency (NHEJ1)." (PMID 35601409, 2022). "SCID related to DNA Ligase 4, Cernunnos- XLF, Nijmegen Breakage Syndrome will be discussed in the section “Radiosensitivity Disorders”." (PMID 34226669, 2021). "Interestingly, in our group, from the patients with suspected high transplant-related toxicity the patients with ataxia-telangiectasia, LIG4 deficiency and SDS did not survive, while two patients with Nijmegen breakage syndrome survived the second HSCT." (PMID 36456809, 2023).
colorectal cancer (12 papers, 2017 to 2024). A primary or metastatic malignant neoplasm that affects the colon or rectum. "The WNT signalling pathway can directly protect against radiation-induced DNA damage causing DNA ligase 4 (LIG4) expression as, for example, it occurs in colorectal cancer." (PMID 37345102, 2023). "Inhibition of LIG4 in colorectal cancer cells using SCR7 inhibitor.Targeting LIG4 by shRNAs in colorectal cancer cell lines." (PMID 34900673, 2021). "Wnt/β-catenin signaling enhances LIG4 expression, and upregulation of LIG4 plays a key role in radioresistance in tissue stem cells and colorectal cancer cells." (PMID 28684677, 2017). "In colorectal cancer, lncRNA lnc-RI enhanced radioresistance through miR-4727-5p/LIG4." (PMID 35600868, 2022). "Furthermore, LIG4 promoter hypermethylation has been shown to contribute to reduced LIG4 expression in colorectal cancer." (PMID 28684677, 2017). "In fact, overexpression of DNA-PKcs, LIG4 and XRCC4 is correlated with poor prognosis in several cancer types, such as esophageal cancer, colorectal cancer, bladder cancer, ovarian cancer, and hepatocellular cancer." (PMID 38380364, 2024). "HCT116 cells (a human colorectal cancer cell line) undergoing a telomeric crisis require the activity of DNA ligase III (LIG3), but not DNA ligase IV (LIG4) to escape a telomere crisis." (PMID 30680069, 2018).